IL6 (interleukin 6)
Diseases named in the same sentence as IL6 in open-access papers (continued):
Sharing a sentence is not in itself a finding about the gene and the disease.
prostate carcinoma (continued). "Specifically, our MR study suggests that long-term IL-6 may increase the risk of prostate cancer and IL-1ra may reduce it." (PMID 36733309, 2023). "A meta-analysis indicated a significant association of the IL-6 gene rs1800795 and rs1800796 polymorphism with an overall elevated risk of prostate cancer based on the information collected from 118 GWAS studies consisting of 50,053 cases and 65,204 control samples." (PMID 36733309, 2023). "Moreover, a case-control study found a positive association between IL-6 levels and prostate cancer risk in normal weight men with 353 cases and 696 controls." (PMID 36733309, 2023). "The first possibility that IL-6 might be associated with prostate cancer progression comes from the discovery that the amount of circulating IL-6 is associated with hormone-refractory or metastatic prostate cancer." (PMID 36733309, 2023). "Furthermore, IL-6/STAT3 signaling has been implicated in the conversion from androgen-sensitive to androgen-resistant prostate cancer via the recruitment of myeloid-derived suppressor cells (MDSCs)." (PMID 36010693, 2022). "The IL-6/IL-6R signaling pathway could be considered a molecular marker associated with the progression of prostate cancer." (PMID 35464825, 2022). "Paracrine interleukin-6 (IL-6) is involved in the induction of neuroendocrine differentiation and mediates the associated features, such as acquisition of a neurite-like phenotype and growth arrest in prostate cancer cells." (PMID 33572108, 2021). "Likewise, prostate cancer cells co-seeded with MSCs were able to survive to hormonal therapy via paracrine IL-6-associated decrease in hormone receptor expression, which was restored through inhibition of IL-6 or JAK pathways." (PMID 34199324, 2021). "While little evidence supports the notion that a high-fat diet increases prostate cancer risk, a high-fat diet may influence disease progression and mortality through interleukin-6 (IL-6)-mediated intratumoral infiltration of MDSCs." (PMID 33800156, 2021). "In addition, the IL-6 -174 G/C polymorphism reportedly enhances the susceptibility of African American men to prostate cancer." (PMID 32859764, 2020). "Several studies have been performed to figure out whether there is an association between prostate cancer and the IL-6 −572G/C polymorphism, but the results are equivocal." (PMID 30602952, 2018). "In prostate cancer, LNCaP and 22Rv1 prostate cancer cells transiently overexpress androgen receptor splice variant-7 (AR-V7), and consequently activate the nuclear factor-kappa B (NF-κB) and upregulate interleukin (IL)-6 gene expression." (PMID 30563247, 2018). "The tumour microenvironment including infiltrating immune cells and stromal tissue including prostate cancer‐associated fibroblasts may also substantially contribute to tumoral IL6." (PMID 29540470, 2018). "The meta-analysis suggested that the GG genotype of IL-6 −572G/C polymorphism might be related to the increased risk of prostate cancer in Asians." (PMID 30602952, 2018). "Moreover, IL-6 is linked to the aggressive phenotype of prostate cancer by regulating the epithelial–mesenchymal transition (EMT) and bone metastasis." (PMID 29795364, 2018). "In summary, the present meta-analysis indicated that the IL-6 −572G/C polymorphism might increase the prostate cancer risk in the Asian population." (PMID 30602952, 2018). "The aim of the present study was to determine whether the interleukin-6 (IL-6) -572G/C polymorphism correlates with prostate cancer." (PMID 30602952, 2018). "Likewise, IL-6 can promote tumorigenesis and is linked to prostate cancer progression and MDSC recruitment." (PMID 29686284, 2018). "Our findings demonstrated that the -572G/C polymorphism of the IL-6 gene may be a risk factor for the development of prostate cancer in Asians." (PMID 30602952, 2018).
prostate carcinoma (continued). "Expression of the atypical PKCλ or PKCι promotes hormone-independent growth of prostate cancer cells through the NF-κB dependent induction of pro-inflammatory proteins like IL-6, and genetic variants of PKCι have been associated with elevated prostate cancer risk." (PMID 30158439, 2018). "The role of IL-6 and IL-1β is implicated in bone metastasis of prostate cancer cells." (PMID 28663562, 2017). "IL-6 is also associated with neuroendocrine differentiation of prostate cancer cells." (PMID 28292326, 2017). "Association between IL-6 rs1800795 polymorphism and prostate cancer susceptibility." (PMID 28296724, 2017). "Emerging evidence indicated that the pro-inflammatory cytokine IL-6 may play a causative role in prostate cancer progression." (PMID 28077171, 2017). "Moreover, our prostate-specific IL-6 transgenic mouse can serve as a valuable model to study inflammation-associated prostate cancer prevention." (PMID 28077171, 2017). "In addition, circulating IL-6 level was associated with progression and death in patients with prostate cancer." (PMID 28783760, 2017). "IL-6 rs1800795 polymorphism may enhance the susceptibility to prostate cancer in African-American men." (PMID 28296724, 2017). "IL-6 is associated with aggressive prostate cancer phenotype and may be involved in the metastatic process through regulation of epithelial-mesenchymal transition and homing of cancer cells to the bone." (PMID 28356100, 2017). "In addition to IL-1 targeting, anakinra reduces the level of IL-6, one of the most common cytokines associated with the progression and metastasis of prostate cancer." (PMID 27429614, 2016). "High IL-6 levels showed association with toxicity from Vorinostat in prostate cancer patients." (PMID 24886605, 2014). "Moreover, studies have shown that stimulation of prostate cancer cell lines with IL-6 or androgen caused increased expression of SOCS members, while a downregulation with small interfering RNA caused inhibition of proliferation and increased apoptotic rate." (PMID 24757565, 2014). "We examined whether IL-6 is involved in the induction of prostate cancer cell migration by cancer-associated 3A6." (PMID 23977098, 2013). "The autocrine production of IL-6 through the downregulation of let-7 miRNA by MSCs, in particular those that are associated with osteolytic prostate cancer, is central to facilitating the adipogenic differentiation of MSCs and for their supporting effects on cancer metastasis." (PMID 23977098, 2013). "However, another study indicated that IL6 causes growth arrest and induces differentiation of the LNCaP androgen-sensitive human prostate-carcinoma cell line." (PMID 23762858, 2013). "T. vaginalis attachment to VECs has also been shown to lead to elevated levels of IL-6, a key inflammatory mediator associated with worse prostate cancer presentation/prognosis and with prostate cancer incidence and mortality among healthy-weight men in a large prospective study." (PMID 22912571, 2012). "In addition, these results clearly showed specific activation of the JAK/STAT pathway by vaccinia virus-encoded hyper-IL-6 in human prostatic cancer cells." (PMID 22236378, 2012). "Likewise, a significant protective effect for high-grade prostate cancer was observed for carriers of the IL6-597 G>A variant (aOR = 0.7, 95%CI: 0.4–1.0)." (PMID 22792137, 2012). "Dysregulated IL-6/JAK2 signaling has also been implicated in prostate cancer tumorigenesis." (PMID 21533169, 2011). "Indeed, high levels of IL6 in the tumour microenvironment are associated with the progression of colorectal, pancreatic, lung and prostate cancer." (PMID 20478049, 2010). "Additionally, IL-6 is associated with aggressive prostate cancer phenotype and may be involved in the metastatic process through regulation of the epithelial–mesenchymal transition (EMT) and homing of cancer cells to the bone." (PMID 39941741, 2025).
prostate carcinoma (continued). "In addition, IL-6 levels were significantly higher in individuals with high-risk prostate cancer." (PMID 36733309, 2023). "By examining the potential pleiotropic effects of IL-related SNPs in PhenoScanner V2, the effects of rs10774624 for IL-27and rs4959106 for IL-6 on smoking, body weight, and high cholesterol may contribute to genetic predisposition to IL levels and prostate cancer." (PMID 36733309, 2023). "The odds ratios (ORs) of prostate cancer were 0.92 (95% confidence interval (CI), 0.89, 0.96; P=1.58×10-05), and 1.12 (95% CI, 1.07, 1.17; P=6.61×10-07) for one standard deviation (SD) increase in genetic susceptibility to IL-1ra, and IL-6 levels, respectively." (PMID 36733309, 2023). "Indeed, inflammation status, including also the release of inflammatory cytokines such as interleukin (IL)-1, IL-6 and IL-17, has been associated with the development and progression of prostate cancer, and androgens have been reported to alter T-cell immunity." (PMID 32580478, 2020). "In addition, zerumbone selectively inhibited the IL-6/JAK2/STAT3 pathway and blocked the prostate cancer-associated genes- cyclin D1, IL-6, COX2 (cytochrome c oxidase), and ETS Variant 1 (ETV1); thereby inducing cytotoxicity through G0/G1 cell cycle arrest and causing apoptosis." (PMID 30781671, 2019). "In addition to IL-1β and IL-6, several other cytokines have been associated with prostate cancer." (PMID 30158439, 2018). "However, the pro-inflammatory cytokines implicated in prostate cancer pathogenesis, including IL-6, TNFa and IL-10, were readily detected in serum at concentrations reported in other mouse lines, and IL-6 was significantly increased in obese compared with lean mice." (PMID 27351281, 2016). "Therefore, the higher risk of high-grade prostate cancer associated with the IL6-597 G-allele may be due to increased IL6." (PMID 22792137, 2012). "Interleukin-6 (IL-6) plays a pivotal regulatory role in prostate cancer progression, contributing to therapy resistance and reshaping of the tumor microenvironment." (PMID 41660621, 2026). "In prostate cancer, the increased cell proliferation and suppressed apoptosis is a response to IL-6." (PMID 40361502, 2025). "An aggressive prostate cancer phenotype and metastasis development are linked to IL-6 through the regulation of epithelial–mesenchymal transition (EMT) and homing of prostate cancer cells to the bone." (PMID 40361502, 2025). "Regarding the anti-inflammatory activity of andrographolide in prostate cancer cells, it has been demonstrated that IL-6 levels are frequently elevated in the serum of many men with advanced, hormone-refractory prostate cancer." (PMID 41465187, 2025). "In this study, the overexpression of SLAMF8 in prostate cancer cells caused an increase in TLR4 expression, triggered the NF-κB signaling pathway, and led to higher IL-6 secretion, potentially contributing to an immunosuppressive tumor microenvironment." (PMID 41162970, 2025). "In prostate cancer, pro-inflammatory cytokines such as interleukin-6 (IL-6), interleukin-8 (IL-8), or transforming growth factor-beta (TGF-β) have been implicated in disease progression and resistance to therapy." (PMID 40149378, 2025). "An increased level of IL-6 negatively correlates with prostate cancer survival and response to chemotherapy in subjects with castration-resistant prostate cancer (CRPC) or untreated metastatic prostate cancer." (PMID 40361502, 2025). "In prostate cancer, IL‐6‐induced STAT3 activation accelerates tumor progression, a condition clinically identified as neuroendocrine‐differentiated prostate cancer." (PMID 40166646, 2025). "Restoration of miR-26a-5p by EZH2 silencing can block the IL-6/STAT3 axis to inhibit prostate cancer growth." (PMID 40652273, 2025).
prostate carcinoma (continued). "Specifically, in prostate cancer, the expression of TLR4 and its association with chronic inflammation, such as that mediated by interleukin-6 (IL-6)." (PMID 41162970, 2025). "IL-6 induces anti-apoptotic Bcl-xL protein expression in highly metastatic prostate cancer cells via STAT3 activation." (PMID 40420174, 2025). "C-reactive protein (CRP), an acute-phase reactant produced by hepatocytes in response to IL-6 signaling, has been extensively studied as an inflammatory biomarker in prostate cancer." (PMID 41555998, 2025). "A low-dose Gnetin C-supplemented diet significantly suppressed levels of pro-inflammatory IL-2, and, to a lesser extent, IL-6, in an early-stage prostate cancer model." (PMID 40077738, 2025). "Within the bone microenvironment, interleukin-6 (IL-6) secreted by bone marrow stromal cells has been shown to induce the upregulation of G6PD expression in prostate cancer cell." (PMID 41514554, 2025). "Previous studies revealed that that adiponectin presents anti-proliferative properties in prostate cancer cells and inhibits dihydrotestosterone-activated cell proliferation, IL-6, and IGF-I." (PMID 39941741, 2025). "In models of prostate cancer, lycopene treatment induces a decrease in the concentration of inflammatory mediators such as TNF-α, IL-1β, IL-6, IL-8, IL-10, and TGF-β associated with a reduction in tumor growth and an increase in survival." (PMID 40420174, 2025). "Many studies identified IL-6 as one of the most important cytokines for predicting normal-tissue radiotoxicity effects, not only in prostate cancer but also across various other malignancies treated with radiotherapy." (PMID 40724564, 2025). "In prostate cancer, the inhibitory effects of pterostilbene on circulating levels of IL-6 and IL-1β were reported in prostate cancer xenografts and transgenic mouse models." (PMID 40077738, 2025). "The findings suggest that CA indirectly inhibits JAK-STAT3 expression in prostate cancer cells by suppressing IL-6 expression." (PMID 39574470, 2024). "Soluble gp130 is a regulator of interleukin-6/soluble interleukin-6 receptor signaling that influences prostate cancer in an interleukin-6-dependent and independent manner." (PMID 39452544, 2024). "STAT3 is a primary downstream regulator of IL-6 expression with its distinctive role in adaptable proliferation and neoplastic transformation in prostate cancer." (PMID 39574470, 2024). "Our study revealed a significant elevation in IL-6 concentration within the prostate cancer group compared to the disease control group, indicating a potential involvement of IL-6 in prostate cancer progression." (PMID 38833027, 2024). "Serum levels of neuron-specific enolase and interleukin-6 were suggested as prognostic factors for castration-resistant prostate cancer with potential clinical utility." (PMID 38305451, 2024). "Another study reported that small-molecule inhibitors of IL-6 signalling decreased the development and proliferation of prostate cancer cells, which is consistent with our findings." (PMID 39554609, 2024). "Several inflammatory indices (IL-6, TNFR2, and CRP) are positively associated with prostate cancer progression." (PMID 39519548, 2024). "Paul Katongole and others also found increased IL-6 levels in the serum of prostate cancer patients." (PMID 38833027, 2024). "It was previously reported that IL-6 in the serum of prostate cancer patients is elevated both in metastatic prostate cancer patients and in CRPC patients." (PMID 38305451, 2024). "The area under the curve (AUC) of IL-6 and IL-17A in the diagnosis of prostate cancer patients were 0.721, and 0.710, respectively, demonstrates “good” capability for discriminating between patients with PCa and controls." (PMID 38833027, 2024). "IL-6 has been shown to have a role in the development and progression of prostate cancer in both in vivo and in vitro studies." (PMID 39452544, 2024).
prostate carcinoma (continued). "The dysmodulation of IL-6 signaling is observed in various cancers, such as breast, lung, liver, and prostate cancer." (PMID 38338683, 2024). "Senescent prostate cancer cells secrete IL‐6, CXCL1 and CXCL2, which inhibit the activity of T cells, including both CD4+ T and CD8+ T cells, thereby promoting prostate tumour growth." (PMID 39270064, 2024). "IL-6 reduced the NK cell-mediated cytotoxicity in castration-resistant prostate cancer by alteration of PD1/NKG2D levels." (PMID 39346912, 2024). "Based on this report, we have noticed that CA impedes the proliferation and migration of prostate cancer cells by inhibiting IL-6 mediated JAK-STAT3 signaling." (PMID 39574470, 2024). "This has sparked significant interest among researchers in targeting key enzymes and signaling pathways involved in the inflammatory response—such as COX-2, NF-κB, IL-6, and IL-1β—as potential therapeutic strategies for prostate cancer." (PMID 39355131, 2024). "IL-6 facilitates the transition from hormone-dependent to castration-resistant prostate cancer by activating androgen receptor signaling." (PMID 39125867, 2024). "Prostate cancer-derived IL-6 can activate fibroblast, and then activated prostate CAFs can secrete MMPs and trigger epithelial mesenchymal transition in cancer cells to facilitate the transformation into CSCs‐like phenotype." (PMID 38644492, 2024). "SRC-1 can functionally promote the transactivation of AR and participate in the ligand-independent activation of AR by IL-6 in prostate cancer cells." (PMID 38553750, 2024). "Zoledronic acid alters the expression of IL-6 in prostate cancer cells and influences osteoclast differentiation through IL-6." (PMID 38041134, 2023). "Numerous studies have supported the IL-6 role in prostate cancer by reporting upregulated IL-6R expression and elevated IL-6 levels in prostatic intraepithelial neoplasia (PIN) and hormone-refractory prostate cancer." (PMID 37680708, 2023). "IL-6 plays an important role in promoting proliferation and anti-apoptosis in prostate cancer cells by upregulating or inhibiting the expression of various signaling pathways in prostate cancer cells." (PMID 37576403, 2023). "Il-6 is a pleiotropic cytokine that in this context, also promotes prostate cancer growth by activating STAT3 signaling." (PMID 36900168, 2023). "As TGF-β, IL-10 and IL-6 are key factors of MDSCs and Tregs mediated immunosuppression, we next evaluated these cytokines at mRNA levels in 32 prostate cancer patients." (PMID 36138265, 2023). "Increases in circulating IL-6 with ADT have been linked to symptoms of fatigue and frailty in prostate cancer patients." (PMID 38256338, 2023). "The overexpression of IL-6 increases the resistance of prostate cancer cells mainly through the JAK/STAT3 axis." (PMID 36982155, 2023). "Abnormal STAT3 activation in prostate cancer cells is linked to EGF receptor and JAK kinase-mediated trafficking of IL-6 and IL-11 cytokines." (PMID 36852795, 2023). "Although few studies on MAOA in stromal cells have been performed, it was suggested that the expression of MAOA is increased in stromal fibroblasts of prostate cancer and that this promotes tumor cell growth through the IL-6/STAT3 signaling pathway." (PMID 37509535, 2023). "The results of these studies clearly show that both in patients with BPH and with prostate cancer, compared to men in the control group, there are statistically significant higher concentrations of pro-inflammatory IL-6." (PMID 37847180, 2023). "Melatonin treatment in LNCaP prostate cancer cells inhibited IL-6 upregulation and suppressed the NFκB-mediated upregulation of AR-V7 demonstrating how the indolamine can impede AR-V7-mediated carcinogenesis and downregulate the receptor variant entirely." (PMID 37191417, 2023). "Like HGF, the rise in IL-6 was profoundly more significant for colorectal cancer patients than breast or prostate cancer patients." (PMID 38067195, 2023).